ALB (albumin)
Diseases named in the same sentence as ALB in open-access papers (continued):
Sharing a sentence is not in itself a finding about the gene and the disease.
glomerulosclerosis (continued). "In this study, STZ-diabetic ETBR-/- mice was characterized by increased serum creatinine and urinary albumin, enhanced glomerulosclerosis, and upregulated ET-1 expression compared with STZ-diabetic WT mice." (PMID 30926764, 2019). "They observed a mild increase in the albumin-to-creatinine ratio and serum creatinine, and a profound increase in glomerulosclerosis and tubulo-interstitial fibrosis in high fat diet mice." (PMID 29615804, 2018). "In comparison to BTBR-WT mice, ob/ob mice demonstrated elevated bodyweight, increased blood glucose/insulin levels, urinary albumin and immunoglobulin G levels, glomerulosclerosis, reduced nephrin abundance and a damaged proximal tubule brush border." (PMID 29244860, 2017). "ADR-treated Cre+/Sirt6fl/fl mice exhibited significant increases in urinary albumin excretion, glomerulosclerosis and podocyte injury, and marked decreases in the levels of nephrin and podocin compared with the ADR-treated Cre+/Sirt6+/+ mice." (PMID 28871079, 2017). "Aged female mice (24 months of age and older) have increased urinary albumin excretion and collagen types I and IV deposition leading to glomerulosclerosis." (PMID 27428057, 2016). "Compared with the age matched WKYs, increased urinary albumin and β2-MG excretion and more extensive profibrogenic genes and proteins expression were observed, gradually develop progressive glomerular sclerosis and interstitial fibrosis." (PMID 27129290, 2016). "The early abnormalities of DN are glomerular hyperfiltration, increased renal albumin permeability followed by the development of glomerular mesangial cell proliferation, extracellular matrix accumulation and glomerulosclerosis." (PMID 25886386, 2015). "db/db mice exhibited higher ratio of urinary albumin to creatinine excretions, higher glomerular sclerosis index, greater glomerular macrophage infiltration, and larger glomerular superoxide than nondiabetic db/m mice." (PMID 25344694, 2014). "Podocyte injury results in glomerular hyperfiltration and increased albumin excretion rate and ultimately leads to glomerular sclerosis seen in DN." (PMID 25166721, 2014). "In conclusion, spironolactone treatment decreased urinary albumin excretion and lessened glomerulosclerosis and tubulointerstitial injury." (PMID 23077601, 2012). "In contrast to albumin/creatine ratios that were completely reversed by the ketogenic diet, histological pathology (e.g., glomerular sclerosis) was only partially (though significantly) reversed by the ketogenic diet in diabetic mice." (PMID 21533091, 2011). "Additionally, monocyte/macrophage-secreted CTSS has been demonstrated to facilitate the activation of protease-activated receptor-2 on glomerular endothelial cells, contributing to inflammation, endothelial damage, albumin leakage, and glomerulosclerosis." (PMID 40115073, 2025). "Moreover, after NXT post-treatment, several feature symptoms including high secreted albumin and ratio of albumin to creatinine in urine, kidney atrophy/hypernephrotrophy, mesangial matrix expansion as well as glomerulosclerosis are all remarkably attenuated." (PMID 38994201, 2024). "Furthermore, 1,25(OH)2D has been shown to reduce glomerulosclerosis and urinary albumin excretion in progressive glomerular damage." (PMID 37153084, 2023). "Successful establishment of the ADR‐injured mouse model was evidenced by significantly higher levels of urinary albumin and serum creatinine, severe glomerular sclerosis and tubular damage and typical podocyte effacement in ADR‐treated group compared with the group of control." (PMID 37395441, 2023). "The unusual presentation prompts consideration of two potential mechanisms for proteinuria pathogenesis in Dent Disease: either diminished reabsorption of physiologically filtered proteins, including albumin, or the presence of glomerular sclerosis suggesting an additional glomerulopathy." (PMID 38049819, 2023).
glomerulosclerosis (continued). "Moreover, our results showed that the number of macrophages was positively correlated with the extent of glomerular sclerosis and negatively correlated with serum albumin." (PMID 34095170, 2021). "Patients with solidified glomerulosclerosis had lower haemoglobin and albumin concentrations; higher serum low-density lipoprotein-cholesterol, and cholesterol concentrations; more severe proteinuria; and a higher prevalence of diabetic retinopathy than those without." (PMID 33633132, 2021). "In addition, we found that deletion of Sirt6 did not affect the protective effect of SV on Ang II-induced urinary albumin excretion, glomerulosclerosis or podocyte injury." (PMID 32642006, 2020). "The patients in the SAb−/GAg − group showed less deteriorated disease markers than in the SAb+/GAg+ group, including albumin levels, 24-h urinary protein, glomerular sclerosis ratio, arteriosclerosis, IgG deposition, C1q deposition, Ehrenreich and Churg’s stage, and a requirement for treatment." (PMID 32674643, 2020). "Another study indicates that NaHS can alleviate glomerulosclerosis symptoms in aging mice mainly by reducing urinary albumin, serum cystatin c, proinflammatories, and renal cortical levels of laminin γ1 (a matrix protein involved in glomerulosclerosis) and by activating AMPK pathway." (PMID 33364941, 2020). "Moreover, the deletion of Sirt6 did not affect the protective effect of SV against Ang II-induced increases in urinary albumin excretion, glomerulosclerosis and podocyte injury." (PMID 32642006, 2020). "Pathological signs such as glomerulosclerosis, tubulointerstitial fibrosis, increased systolic blood pressure, decreased creatinine clearance, and increased albumin-to-creatinine ratios in DSH rats were alleviated by CG200745 treatment compared to those manifestations in positive control animals." (PMID 30691015, 2019). "In the present study, we observed that STZ-diabetic ETBR-/- mice had higher levels of renal damage signs (serum creatinine and urinary albumin), increased mRNA and protein levels of ET-1, enhanced glomerulosclerosis, and increased collagen in the glomeruli in vivo." (PMID 30926764, 2019). "Two mechanisms may be involved in the pathogenesis of NP in Dent disease: defective uptake of physiologically filtered albumin and other proteins, or an additional glomerulopathy as suggested by the presence of glomerulosclerosis on renal biopsy." (PMID 27757584, 2017). "This study demonstrated for the first time that TXL treatment protected SHRs against hypertensive renal injury by reducing the SBP, decreasing urinary albumin excretion, increasing creatinine clearance, and improving glomerulosclerosis and tubulointerstitial fibrosis." (PMID 26673167, 2015). "Moreover, spironolactone treatment reduced urinary protein and albumin excretion and prohibited the glomerulosclerosis which correlated with reduction of CCN2, type I and type IV collagen expression in type 2 diabetes mellitus rat model." (PMID 26421309, 2015). "Our histological results are in line with evidence that the symptoms of diabetic renal disease, for example, renal injury, glomerulosclerosis, interstitial fibrosis, and elevated urine albumin/creatinine ratios, were more pronounced in adult male compared to female diabetic ZSF1 rats." (PMID 25710042, 2015). "There are several studies, which examined the effect of an exogenous MG load, which induced various dysfunctions such as renal problems (urinary albumin excretion, glomerular sclerosis and tubular damage), blood pressure elevation, and diabetic-like pathological changes." (PMID 24402234, 2014). "Modifiers of lysosomal activity may have therapeutic potential in slowing the progression of glomerulosclerosis by enhancing the ability of podocytes to process and degrade albumin." (PMID 24924335, 2014).
glomerulosclerosis (continued). "GFR was negatively correlated to the percentage of global glomerulosclerosis (r = −0.47, P<0.05 n = 19) and albumin excretion correlated with presence of segmental glomerulosclerosis (r = 0.54, n = 18, p<0.05) and extracapillary proliferation (r = 0.59, n = 18, p<0.01)." (PMID 21494642, 2011). "More recently, the daily administration of ethanol to pregnant rats resulted in glomerulosclerosis and interstitial fibrosis of the kidneys of adult offspring, accompanied by elevated levels of serum creatinine, proteinuria, total cholesterol and reduced concentrations of serum albumin." (PMID 30514826, 2019). "In mice with protein-overload induced by bovine serum albumin (BSA), we evaluated whether the alternative pathway (AP) of complement mediated podocyte depletion and podocyte-dependent parietal epithelial cell (PEC) activation causing glomerulosclerosis." (PMID 27345360, 2016). "Furthermore, in our study, the weak negative correlation between degree of microalbuminuria and eGFR may reflect the development of glomerulosclerosis, leading to urine albumin excretion." (PMID 25587544, 2014). "There were statistically significant differences between mild, moderate, and severe glomerulosclerosis (GS) in relation to the presence of SLE, serum creatinine, and serum albumin." (PMID 40713496, 2025). "EMPA and losartan treatment during pregnancy limited the elevated urinary albumin and serum BUN levels and glomerulosclerosis in postpartum PE mice." (PMID 35401209, 2022). "When we challenged PE mice with ADR, PE mice showed elevated urinary albumin and serum BUN levels compared to control mice, and renal histopathology showed a higher percentage of glomerulosclerosis than in control mice." (PMID 35401209, 2022). "The patients with C1qN had higher levels of serum protein and albumin, lower UPCR level, higher percentage of glomerulosclerosis, and higher interstitial fibrosis grade." (PMID 31002691, 2019). "With the alteration of the glomerular filtration barrier, the glomerular structure collapses and leads to an increase in the albumin excretion rate followed by the development of GMC proliferation, ECM accumulation, and glomerular sclerosis." (PMID 25142208, 2014). "miR-30 family members were abundantly expressed in podocytes in normal mice but were downregulated in albumin/TGF-β transgenic mice with podocyte apoptosis and glomerulosclerosis." (PMID 24086574, 2013). "Moreover, the levels of albumin-to-creatinine ratio (ACR) and glomerular sclerosis induced by ADR were attenuated in Elovl7 conditional knockout mice." (PMID 41285716, 2025). "Our model of HFD did not increase albumin or KIM-1 excretion compared to mice on ND, although we found greater glomerulosclerosis and loss of brush border integrity." (PMID 39812779, 2025). "Consistent with the mild increase in glomerular volume and decrease in podocyte density, NPD offspring showed a trend for a mild increase in albumin excretion but no increase in glomerulosclerosis." (PMID 36695822, 2023). "In addition, EMPA treatment during pregnancy limited the elevation of urinary albumin and serum BUN levels, glomerulosclerosis and podocyte damage in response to ADR in postpartum PE mice." (PMID 35401209, 2022). "We should also note that a reduction in glomerulosclerosis in aging Trpc6del/del rats compared to their Trpc6wt/wt littermates did not result in improved urine albumin excretion." (PMID 33918778, 2021). "Previous evidence demonstrated that treatment of Nx rats with the anti-inflammatory nitroflurbiprofen reduces urinary albumin excretion, macrophage infiltration and glomerulosclerosis without any effect on blood pressure." (PMID 25607548, 2015). "However, HPD loading did not lead to higher albumin excretion, glomerulosclerosis or podocyte injury or tubulointerstitial fibrosis in the sham-operated group." (PMID 37175483, 2023).
glomerulosclerosis (continued). "In particular, we did not observe much glomerulosclerosis in the albumin overload model, which may reflect the fact that these experiments were performed on the Sprague Dawley background." (PMID 35805070, 2022). "In T1DM rats, the urinary albumin:creatinine ratio was ∼1.6‐fold greater than that of non‐diabetic control rats (P = 0.02) but we could not detect glomerulosclerosis on histopathological assessment." (PMID 30537108, 2019). "Albumin and alpha-1 globulins were decreased while creatinine, alpha-2 globulins, urine dipstick protein, leukocyte esterase (leukocytes), hemoglobin and red blood cells were all increased in both COL4A3−/− groups compared to WT, thereby confirming the presence of glomerulosclerosis." (PMID 25525413, 2014). "While curcumin administration did not appear to affect albumin excretion, curcumin‐treated SLE mice had less glomerulosclerosis at both 28 and 34 weeks of age when compared to age‐matched vehicle‐treated counterparts." (PMID 32652896, 2020).
osteoporosis (110 papers, 2012 to 2026). A condition of reduced bone mass, with decreased cortical thickness and a decrease in the number and size of the trabeculae of cancellous bone (but normal chemical composition), resulting in increased fracture incidence. "Studies have demonstrated an independent association between osteoporosis and lower serum albumin levels." (PMID 41049358, 2025). "The ALI is primarily composed of neutrophil and lymphocyte counts, albumin levels, and BMI, all of which are closely associated with the onset and progression of osteoporosis." (PMID 41183082, 2025). "An increasing volume of evidence indicates that reduced serum albumin levels are linked to a heightened risk of osteoporosis." (PMID 40069532, 2025). "Future studies should examine these associations using longitudinal and interventional approaches to determine the causal roles of serum Ca and albumin in TyG index and their effects on clinical outcomes in individuals with osteoporosis." (PMID 41019331, 2025). "The association of lower levels of serum albumin with osteoporosis was highly dose responsive, and noted at both the femur neck and lumbar spine, even when confounding variables were accounted for." (PMID 38731106, 2024). "In contrast, lower levels of serum albumin (< 3 g/dL) were strongly linked to the development of osteoporosis in the lumbar spine, femoral neck, and hip." (PMID 36523597, 2022). "Remarkably, in this study, higher serum albumin was significantly associated with lower odds of osteoporosis risk." (PMID 36501153, 2022). "Meanwhile, patients with higher health and diet literacy, education, waist circumference, and greater levels of some biochemical components (albumin, Hb, and Hct) had a lower likelihood of osteoporosis risk." (PMID 36501153, 2022). "Patients with deficiencies in albumin, vitamin D or calcium have a higher risk of developing osteoporosis; therefore, it is recommended that appropriate supplementations be initiated, even if the concentrations of these parameters are only slightly decreased." (PMID 22765843, 2012). "We observed similar results showing that low levels of albumin are more likely to contribute to the development of osteoporosis, although the underlying mechanism remains unclear." (PMID 41480543, 2025). "Notably, low serum albumin has independently predicted osteoporosis and fracture risk, likely through impaired osteoblast activity and diminished antioxidant defense." (PMID 41573203, 2025). "Consequently, further investigations are warranted to clarify the causal relationship and clinical significance between osteoporosis and reduced serum albumin levels." (PMID 38883185, 2024). "The logistic regression analysis showed an association between the serum albumin levels and both H. pylori infection and osteoporosis, suggesting that H. pylori may lead to the development of osteoporosis through abnormal changes in serum albumin." (PMID 38475712, 2024). "Although the study could not definitively confirm a statistically significant causal link between exogenous and endogenous antioxidants and OP risk, it reveals that osteoporosis may contribute to reduced serum albumin levels." (PMID 38883185, 2024). "In this study, we found that higher HL, DDL, and waist circumference, and higher levels of Hb, Hct, albumin, and education, protected our participants from osteoporosis risk, while being female and having comorbid diseases were associated with a higher likelihood of having bone health disorder." (PMID 36501153, 2022). "Besides these demographic characteristics, other studies also considered several routine laboratory tests data, including alkaline phosphatase, calcium, phosphorus, the numbers of hemoglobin and lymphocyte and albumin to predict osteoporosis risk." (PMID 35144529, 2022). "Similarly, in a large population-based outpatient study, lower albumin was independently associated with osteoporosis." (PMID 31912287, 2020).